STAT3 (signal transducer and activator of transcription 3)
Diseases named in the same sentence as STAT3 in open-access papers (continued):
Sharing a sentence is not in itself a finding about the gene and the disease.
breast cancer (continued). "This miRNA has been shown to be downregulated by STAT3 in breast cancer cells." (PMID 31063487, 2019). "inhibited the migration and invasion of breast cancer cells though STAT3/MMP pathway." (PMID 31649548, 2019). "Furthermore, STAT3 signaling participates in the pyruvate kinase isoenzyme type M2-mediated glycolysis of breast cancer cells." (PMID 31655629, 2019). "Indeed, STAT3 has also been implicated in acquired therapy resistance in many cancers including NSCLC, GBM, PDAC, melanoma, and breast cancer." (PMID 31684144, 2019). "could restrain breast cancer metastasis by suppressing Stat3 pathway and recruitment of CD8+ T cells." (PMID 31649548, 2019). "The JAK/Stat3 pathway in human breast cancer drives tumorigenesis and metastasis." (PMID 31658701, 2019). "Altogether, our data suggest that carnosol might exert its effect, at least partly, through inhibition of STAT3 signaling pathway by targeting STAT3 to proteasome degradation in breast cancer." (PMID 31456939, 2019). "Thus, niclosamide is a potent inhibitor of adipocyte-induced EMT in breast cancer cell by inhibiting the IL-6/STAT3 axis in breast cancer cells." (PMID 31383893, 2019). "In addition, the level of p‐STAT3 Y705 in breast cancer cells with SIRT4 transfection and IL‐6 treatment was higher than that in cells with SIRT4 transfection only." (PMID 31573734, 2019). "Blockading of Stat3 inhibited cytokines-induced S100A7 expression in breast cancer cells." (PMID 31731716, 2019). "In conclusion, this study demonstrates the ability of niclosamide to reverse adipocyte induced EMT in MDA-MB-468 (basal) and MCF-7 (luminal) breast cancer cells in part via inhibition of STAT3 phosphorylation and nuclear localization, reducing breast cancer cell migration and invasion." (PMID 31383893, 2019). "Moreover, multi-drug resistant cells of malignant pleural mesothelioma and breast cancer have a constitutively activated ERK1/2/STAT3 pathway that induces the transcription of IDO." (PMID 31117237, 2019). "We previously demonstrated that Manuka honey (MH) inhibits p-STAT3 in breast cancer cells, but the exact mechanism remained unknown." (PMID 31491838, 2019). "RCFE mediated deactivation of Tyr705 phosphorylation of STAT3 inhibited these two critical steps leading to attenuation of metastatic and induction of apoptosis suggesting possible application of this extract against breast cancer therapy." (PMID 31601896, 2019). "JAK2/STAT3 signaling pathway plays a crucial role in the growth of breast cancer cells." (PMID 31540495, 2019). "Breast cancer anti-estrogen resistance 4 promotes the CRC cells stemness through targeting to miR-665/STAT3 signaling and identification of the BCAR4 in CRC stem cells provides a new insight into CRC diagnosis, treatment, prognosis and next-step translational investigations." (PMID 30962766, 2019). "Coculture of breast cancer cells with tumor tissue-derived MSCs (BC-MSCs) led to the development of cisplatin resistance; this process could be associated with the IL-6 secreted by BC-MSCs, which activates STAT3 signaling in breast cancer cells and promotes cell survival." (PMID 30927928, 2019). "The constitutively activated phosphor-Stat3 is responsible for 30–60% of primary breast cancer." (PMID 31019654, 2019). "Finally, our findings reveal new therapeutic targets, including STAT3 and p300, for preventing breast cancer invasion." (PMID 31015465, 2019). "However, some of the STAT3 inhibitors, such as Stattic and WP1066 showed more effective inhibition of STAT3 activation than ODZ10117 in the in vitro results that were analyzed from breast cancer cells, hepatocellular carcinoma cells, and glioma cells." (PMID 31684051, 2019). "C188-9 is an orally bioavailable STAT3 inhibitor that exhibits in vitro and in vivo activity against preclinical models of non-small cell lung cancer, head and neck squamous cell carcinoma, liver cancer, and breast cancer." (PMID 31671769, 2019).
breast cancer (continued). "In fact, STAT3 is persistently activated in more than 40% of breast cancer patients." (PMID 31684051, 2019). "Considering the critical role STAT3 may play in the progression of breast cancer, the alleviated tumor growth in our study may also partially due to the direct inhibition of STAT3 activation in breast cancer cells." (PMID 31040267, 2019). "Additionally, the blockade of IL-6 induced with TB-2-081 increased phosphorylation of the signal transducer and activator of transcription 3 (pSTAT3) in breast cancer cells and reduced osteolytic bone remodeling." (PMID 31847214, 2019). "Finally, we discovered ODZ10117 as a novel STAT3-specific inhibitor and determined its pharmacological activities in both in vitro and in vivo models of breast cancer." (PMID 31684051, 2019). "Previous reports from us and others indicated that STAT3 could promote the proliferation and metastasis of breast cancer cells by EMT pathway." (PMID 31409371, 2019). "We further verified whether ODZ10117 can inhibit tyrosine phosphorylation of STAT3 in breast cancer cells." (PMID 31684051, 2019). "Based on these findings we speculate that IL-6/STAT3 signalling pathway is a key pathway by which adipocytes drive breast cancer migration and invasion." (PMID 31383893, 2019). "Importantly, Stat3 is constitutively activated in about 70% of breast tumors, and these breast cancers are mostly triple-negative breast tumors." (PMID 31649548, 2019). "The impact of Stat3 silencing on PD-L1 levels was explored in a murine model of breast cancer." (PMID 31581535, 2019). "In addition, PL induced apoptosis of breast cancer cells via activation of transcription 3 (STAT3) and phosphatidylinositol 3-kinase (PI3K)/Akt/mammalian target of the rapamycin (mTOR) signaling pathway." (PMID 31739520, 2019). "Furthermore, our results show that adipocyte is capable of activating STAT3 in breast cancer cells evidenced by increased expression of phosphorylated STAT3 (pSTAT3, Y705)." (PMID 31383893, 2019). "These compounds inhibited STAT3-mediated Survivin expression in breast cancer models." (PMID 31752278, 2019). "Above all, STAT3/p-STAT3 expression could induce the occurrence of breast cancer; in breast cancer cells, STAT3 or p-STAT3 overexpression could also predict rapid proliferation, the late stage of TNM and the possibility of lymphatic metastasis." (PMID 31375715, 2019). "Crosstalk between breast cancer cells and conditioned macrophages induced sustained release of pro-inflammatory cytokines from both cell types, activation of NF-κB/STAT3/ERK in the cancer cells and hyperphosphorylation of ERα, which resulted constitutively active." (PMID 30736340, 2019). "While expression of miR-146a is increased in normal mammary epithelial cells, it is decreased in primary breast cancers, relieving miR-146-induced inhibition of STAT3 expression, which could exert its oncogenic functions in breast cancer cells." (PMID 31557902, 2019). "In addition, Ras-induced transformation in bladder and breast carcinoma models exhibit mitochondrial accumulation of STAT3 and more robust cellular glycolysis, a characteristic of cancer cells." (PMID 31684144, 2019). "The constitutive activation of STAT3 is frequently detected in breast carcinoma cell lines." (PMID 31337063, 2019). "Pharmacologic inhibition and gene silencing of STAT3 led to decreased Programmed Death Ligand 1 (PD-L1) expression levels in vitro, and resulted as well in reduction of tumor growth and decreased metastatic dissemination in a mammary carcinoma mouse model." (PMID 31581535, 2019). "PTPN9 also directly interacts with STAT3 and mediates its dephosphorylation in breast cancer cells." (PMID 29558404, 2018). "STAT-3 is overexpressed in several tumor cells, including cholangiocarcinoma, breast cancer, prostate cancer, head and neck squamous cell carcinoma, lymphomas and leukemia, brain tumors, gastric cancer, esophageal cancer, ovarian cancer, nasopharyngeal cancer, and pancreatic cancer." (PMID 30190788, 2018).
breast cancer (continued). "Also, downregulation of STAT3 mRNA in breast cancer cells was noticed following treatment with DE-EDCP when compared to both untreated and cisplatin exposed cells." (PMID 29963272, 2018). "In addition, progranulin inhibition significantly hampered STAT3-mediated oncogenic phenotypes, such as clonogenesis and migratory capacity, in breast cancer cells." (PMID 29914167, 2018). "Consequently, breast cancer tissues with a low miR-519d expression have higher levels of STAT3 protein." (PMID 29875329, 2018). "Consistently, constitutive activation of STAT3 was demonstrated in a wide variety of human tumors, including hematological malignancies, as well as solid tumors, such as head and neck, lung, gastric, hepatocellular, colorectal, prostate, and breast cancers." (PMID 30231553, 2018). "Another example is lncRNAs associated with breast cancer brain metastases (lnc-BM), which binds to JH2 domain of JAK2 protein thus mediate oncostatin-M and signal transducer and activator of transcription 3 (STAT3) phosphorylation by increasing JAK2 kinase activity." (PMID 30018955, 2018). "In addition, Kaplan-Meier analysis demonstrated that the overall survial rate in breast cancer patients with high STAT3 levels was significantly lower than that in those with low STAT3 levels." (PMID 29423040, 2018). "Moreover, S1PR1 can stably activate STAT3 in tumor and bone marrow cells, which is essential for breast cancer cell proliferation, invasion and metastasis." (PMID 30498398, 2018). "In addition, IL-6 has been shown to be a direct regulator for self-renewal of breast cancer cells through signal transducer and activator of transcription 3 (STAT3) activation mediated by the IL-6 receptor/GP130 complex." (PMID 29416638, 2018). "Notably, the pooled effect predicts better breast cancer-specific survival with p-STAT3 overexpression (HR = 0.68, 95% CI: 0.59–0.78, I2 = 30.9%, p < 0.001)." (PMID 29560131, 2018). "In addition, FGF stimulation of the FGFR2-overexpressing breast cancer cell line SUM-52PE also enhanced STAT3 tyrosine phosphorylation and transcriptional activity, which was strongly reduced by FGFR2 knockdown or pharmacologic inhibition." (PMID 29914167, 2018). "Moreover, SP STAT3 mediates the in vivo growth and metastatic potential of murine mammary tumor 4T1 cells by increasing complex I coupling and reducing ROS production." (PMID 30231582, 2018). "In addition, STAT3 signaling is inhibited by niclosamide treatment, leading to cell arrest, growth inhibition, and apoptosis in head and neck, lung, and breast cancer." (PMID 30189637, 2018). "Indeed, silencing of endogenous STAP-2 expression by siRNA strongly reduced BRK-mediated STAT3 activation in T47D breast cancer cells." (PMID 29914167, 2018). "STAT3 signalling in breast cancer cells may confer a survival advantage by promoting aberrant expression of oncogenic target genes." (PMID 29875329, 2018). "Signal transducer and activator of transcription 3 (Stat3) is activated in breast cancer cells and, therefore, may be an effective target for overcoming therapeutic resistance." (PMID 30297887, 2018). "Preclinical data support a role for the IL-6/JAK2/STAT3 signaling pathway in breast cancer." (PMID 29761158, 2018). "Finally, it has been shown that directly targeting STAT3 with piperlongumine has positive and potent effects against breast cancer." (PMID 30839777, 2018). "Moreover, IL-6 secreted by adipose tissue binds to IL-6 receptor on breast cancer cells and activates the Janus family of kinases that phosphorylates signal transducer and activator of transcription-3 (STAT-3)." (PMID 30619088, 2018). "Noteworthily, constitutive activation of STAT3 has been found in various human cancers, such as breast cancer, prostate cancer, ovarian cancer, hepatocarcinoma, and it has shown that activation of STAT3 contributes to tumor cell growth, metastasis and angiogenesis." (PMID 30518397, 2018).
breast cancer (continued). "Although many studies convincingly demonstrated that activation of STAT3 is a critical event in the transformation of established breast cancer cell lines in vitro, the biological, as well clinical, significance of STAT3 activation in human mammary tumorigenesis is less clear." (PMID 30231553, 2018). "Addition of breast cancer-derived exosomes to macrophages results in the activation of the IL-6 response pathway, including phosphorylation of the key downstream transcription factor STAT3." (PMID 29867925, 2018). "We, thus, hypothesized and tested whether inhibiting STAT3 activity in the context of surgery-induced inflammation could result in efficient targeting of these residual breast cancer cells with stem-like phenotypes." (PMID 30231553, 2018). "A recent study revealed that Ki-67 and STAT3 might be promising therapeutic targets in cancer, including breast cancer." (PMID 29963272, 2018). "Our data indicate that Stat3 could be a potential target and MSCs could provide a basis for a promising therapeutic strategy for radiotherapy of breast cancer." (PMID 30297887, 2018). "One signaling pathway that we found to be strongly induced in breast cancer cells when cultured in the presence of surgical essudates (wound fluids (WF) drained from breast of patients for 24 hours after removal of primary tumor) was the STAT3 pathway." (PMID 30231553, 2018). "However, only the N stage, which positively correlates with STAT3 expression, was identified as the independent predictor of the overall survival (OS) of patients with breast cancer." (PMID 29560131, 2018). "First, subgroup analysis was performed to estimate whether biomarkers (STAT3 and p-STAT3) of breast cancer are different from the analysis above." (PMID 29560131, 2018). "It is to note that inactivating mutations in the JAK2/STAT3 pathway were never identified in previous exome studies of primary breast cancer, despite quite a number of large and deep analyses being carried out so far." (PMID 30231553, 2018). "However, both Sonnenblick A. (2013) and Liu X. (2014) testified that p-STAT3 is a marker of good prognosis in breast cancer." (PMID 29560131, 2018). "Findings of this study indicate that suppressing the Stat3 signaling pathway combined with traditional radiotherapy could be a promising novel approach for overcoming radioresistance in MDA-MB-231 breast cancer cells." (PMID 30297887, 2018). "Whilst mammary neoplasia is not a disease that is limited to humans, relatively sparse data currently exist regarding the importance of STAT3 activity in mammary tumours in animals, particularly when considering studies correlating pSTAT3 expression directly with clinical outcome." (PMID 29875329, 2018). "Similarly, mice harbouring a constitutively active STAT3 allele (STAT3C) in a transgenic MMTV-Neu (ErbB2) background, exhibited more invasive mammary tumours with earlier onset than those with wild-type STAT3 alleles." (PMID 29875329, 2018). "Deletion or decreased expression of mitochondrial CypD activated interorganelle signaling in glioblastoma and breast cancer cell lines, leading to transcriptional changes in gene expression, modulation of a chemokine/chemokine receptor signature, and STAT3 activation." (PMID 29914167, 2018). "Previous studies with breast carcinoma cells indicated that STAT3 could be a molecular target for C12-HSL." (PMID 29854771, 2018). "Finally, we have demonstrated that a subset of equine mammary carcinomas, which are rare but frequently aggressive tumours, exhibit nuclear localization of STAT3." (PMID 29875329, 2018). "Therefore, through interaction with aVb3 integrin, it can trigger metastatic activity or cell growth via activation of the FAK/AKT pathway in lung cancer or activation of the JAK/STAT3 pathway in breast cancer." (PMID 29254164, 2017).
breast cancer (continued). "Additionally, our data provide evidence for the role played by Syndecan-1 in synchronously fine tuning multiple signaling pathways including IL-6/STAT3/gp130, inflammatory cytokines, Notch, and EGFR, implicated in breast cancer stemness." (PMID 28270211, 2017). "Finally, selective loss of pY313-ShcA signalling exposes breast cancer cells to basally enhanced STAT1 and STAT3 signalling, to favour immune suppression." (PMID 28276425, 2017). "We examined whether BENDA suppressed both the DNA-binding and transcriptional activity of STAT3 in human breast cancer cells expressing activated STAT3." (PMID 28125678, 2017). "Moreover, in breast cancer cells, activated STAT3 promoted invasion and brain metastasis by suppressing Cav-1 transcription by directly binding to its promoter." (PMID 29221162, 2017). "Compared with normal controls, the expressions of FAK, Src, ERK1/2 and Stat3 are up-regulated, while the expressions of PPARγ, C21orf34 and E-cadherin are down-regulated in TCGA Breast Cancer and Turashvili Breast Cancer." (PMID 28108732, 2017). "Although MT/Shc2F/2F breast cancer cells display reduced Y705-STAT3 phosphorylation in vitro, progressively growing MT/Shc2F/2F tumours (PD) that evolved in an immunocompetent background hyperactivated STAT3 compared with those that emerged in IFNγ−/− mice." (PMID 28276425, 2017). "Here, we observed that STAT3 exerted anti-apoptotic effects in breast cancer cells." (PMID 28178652, 2017). "While no obvious changes were observed in the phosphorylation levels of STAT1 and STAT5, a conclusion may be safely conducted that PMM-172 primarily suppressed STAT3 activation in STAT3-dependent breast cancer cells." (PMID 28588262, 2017). "TIMP1, a known transcriptional target of STAT3, carries complex regulatory role in breast cancer." (PMID 28333977, 2017). "Moreover, CSE was decreased markedly both at mRNA and protein levels when STAT3 was knockdown in breast cancer cells." (PMID 29029463, 2017). "STAT3 is highly expressed and activated in most breast cancers, especially in TNBC." (PMID 28594363, 2017). "In addition to inhibiting MCL-1, SC-2001 has been reported to induce cell death through SHP-1 dependent STAT3 inactivation in liver and breast cancer cells." (PMID 27086916, 2017). "Similarly, in breast cancer cells and Hep3B hepatoma cells, complexes constituted by STAT3, CBP/p300, RNA polymerase II (Pol II), and HIF-1α are reported to regulate HIF-1α target genes including VEGF." (PMID 28978186, 2017). "Interestingly, miR-20a was found to act as a tumor suppressor in breast cancer and inhibit the proliferation and invasion of pancreatic cells by negatively regulating STAT-3 protein expression due to its possible double-sided role in tumors." (PMID 28466015, 2017). "This is consistent with our observations that mammary epithelial STAT3 loss profoundly impairs breast cancer development in immunocompetent, but not immunodeficient, mice." (PMID 28276425, 2017). "TFF3 has previously been reported to act through STAT3 to stimulate breast cancer metastasis." (PMID 29100386, 2017). "Given these different growth patterns, we also examined how perturbation in phosphotyrosine-dependent ShcA signalling impacts the STAT1 and STAT3 activation status of mammary tumours that display immune surveillance (MT/Shc2F/2F) versus suppression (MT/ShcA+/+ and MT/Shc313F/313F) phenotypes." (PMID 28276425, 2017). "In contrast, STAT3 loss in MT/Shc313F/313F mammary tumours did not affect tumour onset but delayed the growth of established tumours, specifically in a CD8+/+ background." (PMID 28276425, 2017). "However, the significance of TNF-α in regulation of TNFR1/NF-κB (and/or p38)/p-STAT3 in breast cancer is elusive." (PMID 28938560, 2017). "We suggest that the development of inhibitors that bind the Y239/240-ShcA phosphorylation sites may represent an alternative therapeutic strategy to inhibit STAT3 activation in breast cancer cells." (PMID 28276425, 2017).